G6PD (glucose-6-phosphate dehydrogenase)
Diseases named in the same sentence as G6PD in open-access papers (continued):
Sharing a sentence is not in itself a finding about the gene and the disease.
G6PD deficiency (continued). "Further studies should test the predicted safety for G6PD-deficient infants suggested here by monitoring breastfed infants with G6PD deficiency during maternal PQ treatment." (PMID 29590311, 2018). "With respect to haematological characteristics, the mean Hb was 11.0 ± 1.4 g/dL, whilst 182 (5.8%) and 191 (6.1%) of the pregnant women had sickle cell trait and glucose-6-phosphate dehydrogenase (G6PD) deficiency, respectively." (PMID 30344800, 2018). "The Carestart G6PD biosensor represents a significant improvement for quantitative diagnosis of G6PD deficiency over previous versions." (PMID 29738562, 2018). "The prevalence of G6PD deficiency amongst sufferers in this region is high and a small number have G6PD mutants of diminished function in the presence of apparently normal G6PD levels." (PMID 29338726, 2018). "Several other point-of-care tests for G6PD deficiency are also in development on different platforms, such as the Access Bio CareStart G6PD Biosensor (Somerset, NJ, USA) and the FINDER platform from Baebies (Durham, NC, USA)." (PMID 31709308, 2018). "The aim of this study is to assess the disease incidence and mutation spectrum of glucose-6-phosphate dehydrogenase (G6PD) deficiency in Guangxi, China, and to determine an optimal cutoff value to identify heterozygous female neonates." (PMID 29339739, 2018). "A prevalence of 13% (33/248) G6PD deficiency was observed in the cohort by G6PD RDT whilst by genotypic assessment, 32% (79/248) were A+ and 3.2% were A−, respectively." (PMID 29558929, 2018). "Glucose-6-phosphate dehydrogenase (G6PD) deficiency is an X-linked inherited disorder with a worldwide prevalence of 4.9% and the disorder affects 400 million people globally." (PMID 30097005, 2018). "To date, more than 400 G6PD variants have been identified, of which 186 variants are associated with G6PD deficiency by decreasing the activity or stability of G6PD." (PMID 30918572, 2018). "The advent of these new G6PD testing technologies raises new opportunities to address inequity in access to newborn screening in countries with high G6PD deficiency prevalence." (PMID 31709308, 2018). "More than 400 G6PD variants have been identified up to date, of which 186 variants are linked to G6PD deficiency by decreasing the activity or stability of G6PD." (PMID 29548282, 2018). "The information available at present (2017) about G6PD deficiency prevalence and variants of the G6PD gene among Sri Lankans is very sparse." (PMID 29540210, 2018). "Glucose 6-phosphate dehydrogenase (G6PD) deficiency, the most common human enzymopathy, is prevalent in tropical and subtropical areas where malaria is or was endemic." (PMID 29672516, 2018). "The CareStartTM G6PD deficiency RDT test kit was used for phenotypic evaluation of G6PD status in the test population, to explore its utility as point-of-care tool." (PMID 29558929, 2018). "Primaquine (PQ) use must be informed by safety considerations, as this drug causes dose-dependent hemolysis in individuals with enzymatic glucose-6-phosphate dehydrogenase (G6PD) deficiency, the most commonly inherited enzyme deficiency worldwide." (PMID 29342267, 2018). "Neonates suspected for G6PD deficiency were further analyzed by quantitatively enzymatic assay and G6PD mutation analysis." (PMID 29339739, 2018). "The 8-aminoquinoline antimalarials, the only drugs which prevent relapse of vivax and ovale malaria (radical cure), cause dose-dependent oxidant haemolysis in individuals with glucose-6-phosphate dehydrogenase (G6PD) deficiency." (PMID 29677199, 2018). "We present a rare case of rasburicase-induced methemoglobinemia and hemolytic anemia in the setting of presumed glucose-6-phosphate dehydrogenase (G6PD) deficiency." (PMID 30324040, 2018). "The male predominance of G6PD deficiency can be attributed to the X-linked inheritance in G6PD gene." (PMID 30918572, 2018).
G6PD deficiency (continued). "Whilst these results are reassuring, a number of qualitive G6PD diagnostics already available are capable of diagnosing G6PD deficiency at the same threshold with comparable accuracy at lower costs." (PMID 30388146, 2018). "Three patients had missense mutations in G6PD (Val291Met, Asn126Asp, Asp194Glu), however, only one mutation (Val291Met) results in a severe G6PD deficiency." (PMID 30161219, 2018). "Glucose-6-phosphate dehydrogenase (G6PD) deficiency is one of the most common X-linked genetic blood disorders in the world, impacting more than 400 million people." (PMID 31709308, 2018). "The information available at present (2017) about G6PD deficiency prevalence and variants of G6PD gene among Sri Lankans are very sparse." (PMID 29540210, 2018). "Clinical manifestations caused by these G6PD variants vary from severe to asymptomatic and G6PD deficiency can be usually assessed by enzymatic and/or genetic assays." (PMID 29548282, 2018). "The major causes of severe hyperbilirubinaemia were idiopathic (33.3%), sepsis (35.3%), ABO incompatibility (17.6%) and glucose-6-phosphate dehydrogenase (G6PD) deficiency (11.8%)." (PMID 29935542, 2018). "In settings with poor access to care, prematurity and Glucose-6-phosphate dehydrogenase (G6PD) deficiency are important causes of INH." (PMID 29895274, 2018). "Since the G6PD gene maps to the X chromosome (of which males have only one), a male with a mutation (called a hemizygote) causing G6PD deficiency will have full expression of the defect." (PMID 29499733, 2018). "The mutation in patient N28 was described previously and is known to be associated with a G6PD deficiency, our results indicate 68% drop in G6PD activity in this individual." (PMID 30161219, 2018). "G6PD deficiency is caused by point mutations in the coding region of the G6PD gene in the X chromosome." (PMID 29540210, 2018). "The main adverse effect of primaquine is dose-dependent haemolysis in glucose 6-phosphate dehydrogenase (G6PD) deficiency, the most common human enzymopathy." (PMID 29672516, 2018). "While G6PD deficiency can be diagnosed by qualitative tests in both males and females, female patients with intermediate G6PD activity who are at risk of hemolysis cannot be diagnosed reliably by current qualitative tests." (PMID 29738562, 2018). "In some studies, hereditary anaemia such as sickle cell blood and glucose-6-phosphate dehydrogenase (G6PD) deficiency were found at a high rate among the Rajbanshi people." (PMID 28535765, 2017). "Radical cure of Plasmodium vivax malaria with 8-aminoquinolines (primaquine or tafenoquine) is complicated by haemolysis in individuals with glucose-6-phosphate dehydrogenase (G6PD) deficiency." (PMID 28170391, 2017). "G6PD deficiency, caused by mutations on the X-linked G6PD gene, is mainly asymptomatic unless affected individuals are exposed to certain medicines or foods that induce oxidative stress." (PMID 29181452, 2017). "The concentration of GSH and the ratio of GSH/GSSG in blood measured using MS/MS on the first day of sample preparation are consistent with G6PD activity and are helpful for diagnosing G6PD deficiency." (PMID 28728551, 2017). "Sensitivity of cord blood in screening for G6PD deficiency, using peripheral G6PD assay as a gold standard was 98.6% with a NPV of 99.5%." (PMID 28693459, 2017). "This study revealed high prevalence of co-inheritance of G6PD deficiency with HbAE in the Kachin ethnicity, and a potential interaction of the G6PD Mahidol 487G>A and HbAE in males leading to severe anemia." (PMID 28531196, 2017). "G6PD deficiency is genetically heterogeneous with 186 different allelic mutations in the G6PD gene that have been identified, generating more than 400 different enzyme variants as reported on the basis of diverse biochemical characteristics." (PMID 28152025, 2017).
G6PD deficiency (continued). "Glucose-6-phosphate dehydrogenase (G6PD) deficiency (G6PDd) is a widespread enzyme deficiency that affects approximately 400 million people worldwide." (PMID 28676055, 2017). "We sought to determine the incidence and gender distribution of G6PD deficiency, and compare the results of cord against peripheral blood in identifying G6PD DEFICIENCY neonates using quantitative enzyme activity assay." (PMID 28693459, 2017). "We report a case of new onset retinitis pigmentosa (RP) associated with a glucose-6-phosphate dehydrogenase (G6PD) deficiency in a 63-year-old African-American male who presented with worsening night vision over a period of five years." (PMID 28948126, 2017). "The incidence of G6PD deficiency is 7.2–13.7% in this population, and between 2008 and 2011 eight neonates died of kernicterus, four of whom were G6PD deficient." (PMID 27576869, 2017). "Glucose-6-phosphate dehydrogenase (G6PD) deficiency is an X-linked hereditary enzymatic abnormality that affects more than 400 million people worldwide." (PMID 28103889, 2017). "The clinical hemolytic episode of G6PD deficiency is varied, ranging from mild and self-limiting to severe and even fatal, depending on exposure and the G6PD genotype." (PMID 28583873, 2017). "The aim of this study was to determine the prevalence of G6PD deficiency, and associated G6PD genotypes, in adults with falciparum malaria in southern Bangladesh." (PMID 28356147, 2017). "The male preponderance of G6PD deficiency can be attributed to the X-linked inheritance in G6PD gene." (PMID 28535765, 2017). "The feasibility of using lyophilized recombinant human G6PD as a QC reagent in novel point-of-care tests for G6PD deficiency is demonstrated." (PMID 28552983, 2017). "Among the 8139 neonates with cord blood G6PD assays, an overall incidence of 2% for G6PD deficiency was computed." (PMID 28693459, 2017). "Many countries, however, do not administer primaquine due to fear of hemolysis in those with glucose-6-phosphate dehydrogenase (G6PD) deficiency." (PMID 28542194, 2017). "In the present study, with the prevalence of HbE at 39% and G6PD deficiency at 24%, 22% of the study population was found to have co-inherited the HbE and G6PD 487G>A variant." (PMID 28531196, 2017). "In one cohort comparing G6PD deficient and replete people there was a greater fall with G6PD deficiency (MD −4.99%, 95% CI −9.96 to −0.02)." (PMID 28830424, 2017). "Glucose-6-phosphate dehydrogenase (G6PD) deficiency and hemoglobin E (HbE, β26 Glu-Lys) are two common red cell disorders in Southeast Asia." (PMID 28531196, 2017). "The point-of-care diagnosis of G6PD deficiency is usually made by a phenotypic screening test in which the G6PD-mediated reduction of NADP+ to NADPH is measured semiquantitatively." (PMID 28170391, 2017). "On BinaxNOW ® G6PD test, higher G6PD deficiency was found associated with male (53/1341; 10.2%) compared to female (44/820; 5.4%) (p = 0.001)." (PMID 28535765, 2017). "Kernicterus and severe hyperbilirubinemia are strongly associated with glucose-6-phosphate dehydrogenase (G6PD) deficiency and can be exacerbated by haemolytic agents such as menthol and naphthalene." (PMID 27576869, 2017). "The aim of this study was to determine the prevalence of G6PD deficiency and associated G6PD deficient genotypes in adults with falciparum malaria presenting at two locations in Chittagong Division." (PMID 28356147, 2017). "Glucose-6-phosphate dehydrogenase (G6PD) deficiency is a commonly pervasive inherited disease in many parts of the world." (PMID 28079896, 2017). "The beneficial effects of inhibition of multiple ipla genes by RNAi in G6PD deficiency supports the notion that G6PD deficiency enhanced iPLA activity which in turn altered the glycero phospholipid metabolism and membrane integrity during embryogenesis." (PMID 28079896, 2017).
G6PD deficiency (continued). "The impact of switching to the screening strategy was slightly less in females due to the exclusion of pregnant women from primaquine treatment and the low sensitivity of the G6PD RDT in women with intermediate G6PD deficiency." (PMID 28542194, 2017). "Lyophilized r-G6PD enzyme is stable and can be used as a control for point-of-care tests for G6PD deficiency." (PMID 28552983, 2017). "The CareStartTM G6PD Biosensor was less well correlated with the gold standard, and a poor predictor of G6PD deficiency." (PMID 28121993, 2017). "Glucose-6-phosphate dehydrogenase (G6PD) deficiency, an X-chromosome-linked genetic disorder, is the most prevalent mutation in humans, affecting more than 400 million people worldwide." (PMID 28728551, 2017). "G6PD screening by both qualitative and quantitative tests led to the exclusion of 5 persons with severe G6PD deficiency (WHO Class I or II, less than 10% of normal G6PD activity) prior to enrollment." (PMID 28591198, 2017). "It is also recommended to measure G6PD level of hepatitis A patients who are unaware of their G6PD level in malarious areas and regions with highly prevalent G6PD deficiency." (PMID 28875002, 2017). "PQ compared to placebo in G6PD deficient people Two trials provide data for this, using a single dose of PQ versus placebo in people with G6PD deficiency." (PMID 28830424, 2017). "While G6PD deficiency is very common in malaria-endemic areas, G6PD testing is generally unavailable because the standard point-of-care test requires appropriate reagents, electricity, trained staff, and quality controls." (PMID 28170391, 2017). "Hematological disorders affected 11.24% of the patients, in which Glucose-6-Phosphate Dehydrogenase (G6PD) deficiency occurred 14.29% of the BA male patients, whereas ~4.8% of males in the Hong Kong have the condition." (PMID 28416017, 2017). "The concentration of GSH and the ratio of GSH/GSSG in the blood, as measured using MS/MS on the first day of sample preparation, are consistent with the G6PD activity and are helpful for diagnosing G6PD deficiency." (PMID 28728551, 2017). "Glucose-6-phosphate dehydrogenase (G6PD) deficiency is an X-linked disorder that affects as many as 400 million people worldwide, making it the most common enzymatic defect." (PMID 28235023, 2017). "PQ compared to placebo in G6PD deficient people Three randomized trials report 0.75 mg/kg PQ versus placebo in people with G6PD deficiency, all part of larger trials." (PMID 28830424, 2017). "Given the higher 0.75mg/g dose, we performed universal G6PD screening and excluded 5 volunteers with severe G6PD deficiency (<10% of normal activity)." (PMID 28591198, 2017). "The perceived low prevalence of G6PD deficiency and reduced incidence of P. vivax infection lead many respondents to question the cost-effectiveness of routine G6PD testing." (PMID 28797255, 2017). "Available data related to G6PD in Cameroon are scarce, with one published survey reporting the G6PD deficiency prevalence being 6.6%." (PMID 28196496, 2017). "Primaquine at higher doses causes acute haemolytic anaemia in G6PD-deficient patients, but there is limited information about the safety of the lower dose in populations where G6PD deficiency is common." (PMID 28605472, 2017). "Target product profile for quality control reagents to support point-of-care diagnostic tests for glucose-6-phosphate dehydrogenase (G6PD) deficiency." (PMID 28552983, 2017). "Glucose-6-phosphate dehydrogenase (G6PD) deficiency is an X-linked enzyme deficiency present in more than 400 million people worldwide." (PMID 28356147, 2017). "The focus was only on the G6PD mutations 202G > A and 376A > G, although other variants such as A542T, G680T or T968C have also been reported to contribute to G6PD deficiency, albeit at far lower frequencies." (PMID 27388012, 2016).
G6PD deficiency (continued). "A study of a Cambodian population (n = 938) having 7.9% G6PD deficiency dominated by the Viangchan variant (92%) reported good performance of the G6PD RDT relative to the FST." (PMID 26894297, 2016). "A significant association was observed between gender and G6PD status in patients with malaria (P < 0.05, OR = 5.167), with the incidence of G6PD deficiency being higher in males than in females." (PMID 27109515, 2016). "In the present study, at the G6PD cut-off-activity of ≤30 % of normal, gender of children was a significant independent predictor for G6PD deficiency." (PMID 27329471, 2016). "Our findings highlight the need for better understanding of G6PD deficiency across the life course for the large numbers globally with G6PD." (PMID 27824927, 2016). "G6PD gene sequencing confirmed that the frequency of G6PD deficiency for the study population was 9.9%." (PMID 27880809, 2016). "Primaquine causes seriously threatening acute hemolytic anemia in patients having inherited glucose-6-phosphate dehydrogenase (G6PD) deficiency." (PMID 26894297, 2016). "A systematic search was implemented using four literature databases (PubMed, Embase, Science Direct and Web of Science) to capture all the causative mutations of Glucose-6-phosphate dehydrogenase (G6PD) deficiency (G6PDD) in the 22 Arab countries." (PMID 27853304, 2016). "This toxicity is a significant public health concern because G6PD deficiency affects approximately 400 million people worldwide who live mostly in malaria-endemic countries, where the median G6PD deficiency allele prevalence was 8 %." (PMID 27109515, 2016). "It is recommended that the performance of the CareStartTM G6PD RDT is also evaluated for the detection of G6PD deficiency among malaria-infected patients compared to normal controls." (PMID 27329471, 2016). "Primaquine is contraindicated in infants and pregnant women, and individuals with glucose-6-phosphate dehydrogenase (G6PD) deficiency." (PMID 27708188, 2016). "Glucose-6-phosphate dehydrogenase (G6PD) deficiency is a common X-linked recessive genetic disorder inherited from parents." (PMID 27880809, 2016). "This is likely caused by the G6PD deficiency protecting against malaria, however, this study cannot conclude the role of G6PD deficiency against malaria because only a small number of patients with a G6PD deficiency was recruited and studied." (PMID 27109515, 2016). "Although the International Committee for Standardization in Haematology (ICSH) recommends the FST for determining G6PD deficiency, the quantitative G6PD enzymatic assay remains the reference method." (PMID 27329471, 2016). "Mutations that are distributed throughout the g6pd gene lead to a hereditary disease at the population level known as G6PD deficiency." (PMID 27941691, 2016). "Detectable parasitaemia was significantly less prevalent in the 66 (2.6%) individuals with severe or intermediate G6PD deficiency compared to those who were G6PD normal (OR = 0.44 [95%CI: 0.24–0.80]; p = 0.005)." (PMID 27788243, 2016). "Indonesia's hugely diverse human population carries many variants of glucose-6-phosphate dehydrogenase (G6PD) deficiency, most of them exhibiting severely impaired enzyme activity." (PMID 27708185, 2016). "Alternatively, the findings of the present study show the good performance of CareStartTM G6PD RDT for detecting severe G6PD deficiency compared to the reference method among children in rural, malaria-endemic areas of Hodeidah governorate." (PMID 27329471, 2016). "The prevalence of G6PD with ≤60 % of normal activity among children residing in malaria-endemic areas of Hodeidah governorate is 12.0 %, with about 2.3 % having severe G6PD deficiency of ≤10 % of normal activity." (PMID 27329471, 2016). "Primaquine and other 8-amnoquinoline based anti-malarials can cause haemolysis in subjects with glucose-6-phosphate dehydrogenase (G6PD) deficiency." (PMID 27035821, 2016).